ZKSCAN8 (zinc finger with KRAB and SCAN domains 8)
Description:
May be involved in transcriptional regulation.
Synonyms: ZNF192; LD5-1; ZSCAN40
Tractability: PROTAC: UniProt records ubiquitination sites on it; ubiquitination databases record sites on it.
Gene: Protein-coding gene on chromosome 6 (28,141,732 to 28,159,461, forward strand). Ensembl gene ENSG00000198315.
Subcellular location: Nucleus
Subcellular location (Human Protein Atlas): Nucleoplasm; Cytosol
Pathways (Reactome):
Gene expression (Transcription): Generic Transcription Pathway
Gene Ontology:
Molecular function: protein binding; DNA-binding transcription factor activity, RNA polymerase II-specific; RNA polymerase II cis-regulatory region sequence-specific DNA binding; sequence-specific double-stranded DNA binding
Biological process: regulation of transcription by RNA polymerase II; regulation of DNA-templated transcription
Cellular component: nucleus; cytoplasm
Genetic constraint (gnomAD): Loss-of-function variants: 27 observed, 59.43 expected, observed/expected ratio (o/e) 0.45, 90% interval 0.33 to 0.63. The upper end of that interval is the gene's LOEUF score, 0.63, which puts it in group 2 of 6, group 1 being the genes least tolerant of losing a copy. Missense variants: 597 observed, 735.72 expected, observed/expected ratio (o/e) 0.81, 90% interval 0.76 to 0.87. Synonymous variants: 214 observed, 262.02 expected, observed/expected ratio (o/e) 0.82, 90% interval 0.73 to 0.92.
Homologues: Orthologues: chimpanzee ZKSCAN8 (99% identical), macaque ZKSCAN8 (98% identical), pig ZKSCAN8 (94% identical), dog ZKSCAN8 (94% identical), rabbit ZKSCAN8 (93% identical), rat Zkscan8 (88% identical), mouse Zkscan8 (88% identical), guinea pig ZKSCAN8 (85% identical). Paralogues in human: ZNF397 (47% identical), ZSCAN12 (44% identical), ZKSCAN1 (43% identical), ZKSCAN3 (42% identical), ZKSCAN4 (40% identical), ZSCAN30 (39% identical), ZSCAN21 (39% identical), ZSCAN26 (38% identical), ZSCAN31 (38% identical), ZNF394 (36% identical), ZSCAN22 (36% identical), ZNF165 (35% identical), and 18 more.
Diseases named in the same sentence as ZKSCAN8 in open-access papers:
ZKSCAN8 is named in the same sentence as 5 diseases in open-access papers, as found by Europe PMC text mining. Sharing a sentence is not in itself a finding about the gene and the disease.
ZKSCAN8 shares sentences with these, for which no sentence is quoted: asthma (1 paper); breast carcinoma (1); infection (1); leishmaniasis (1); schizophrenia (1).